NRXN1 (neurexin 1)
Diseases named in the same sentence as NRXN1 in open-access papers (continued):
Sharing a sentence is not in itself a finding about the gene and the disease.
cancer (14 papers, 2015 to 2024). A tumor composed of atypical neoplastic, often pleomorphic cells that invade other tissues. "In our study, NRXN1 knockdown was shown to induce GSK3β phosphorylation at Ser9, which aligns with the established role of GSK3β in cancer progression." (PMID 39518976, 2024). "We could detect mutations on NRXN1 and NRXN3 in 950 cancer samples across 32 cancer types." (PMID 35052689, 2021). "For instance, NOVA1, NRXN1, TMEM132C, USP44, VIPR2, and ZSCAN23 were consistently downregulated in nine cancers." (PMID 28060724, 2017). "Deletions in many of our hotspot genes (e.g., NRXN1, PDE4D, WWOX, LSAMP, and NEGR1) are also found in numerous cancers where they likely represent the effects of perturbed replication and transcription." (PMID 25373142, 2015). "However, analysis of the effect of NRXN1 knockdown on cancer cell invasion revealed a significantly increased invasive capacity in CRC cell lines, such as HCT116, NT29, and Caco2, upon NRXN1 knockdown." (PMID 39518976, 2024). "While, difference in the expression of GNGT1 and NRXN1 was not significant in NPC samples compared with non-carcinoma samples." (PMID 34544905, 2021).
neurological diseases (13 papers, 2014 to 2025). "Noteworthy, both increased and decreased expression of NRXN1 is associated with neurological diseases." (PMID 36084040, 2023). "The NRXN1 gene which interacts with its postsynaptic binding partner at the synapse has been associated with neurological diseases." (PMID 24410907, 2014). "NRXN1 dysfunction is closely related to a variety of neurological disorders." (PMID 36737720, 2023).
brain diseases (4 papers, 2019 to 2025). "The target mutations associated with brain disorders could destabilize human NRXN1 protein." (PMID 35627176, 2022). "Almost half of them were involved in axon-related processes (RTN4R, CNTNAP4, ADAM22, PCSK1N, NRXN1), which could indicate that the neurodegenerative mechanisms may be different between these brain diseases." (PMID 33603109, 2021).
cardiovascular diseases (1 paper, 2020). "Read in conjunction, NRXN1 may induce cardiovascular diseases through some mechanism, and further exploration is needed to lucubrate the cardiovascular function of NRXN1." (PMID 33224271, 2020).
infection (1 paper, 2021). The state of being infected such as from the introduction of a foreign agent such as serum, vaccine, antigenic substance or organism. "Single cell self-renewal of ES cells in this substrate-adherent 21 day assay, after partial knock-down of neurexin-1, was not significantly different to that in shControl infected cells, likely reflecting decreased viability of patient-derived primary ES cells after infection with shRNA." (PMID 34403115, 2021).
NRXN1 also shares sentences with these, for which no sentence is quoted: bipolar disorder (5 papers); speech delay (5); colorectal cancer (2); diabetes (2); genetic disorders (2); heart disease (2); hepatocellular carcinoma (2); Klinefelter syndrome (2); mood disorder (2); neurodegenerative disease (2); Pitt Hopkins-like syndrome (2); thyroid cancer (2); Type-1 diabetes (2); 22q11.2 deletion syndrome (1); agnosia (1); alcohol abuse (1); alcoholism dependence (1); amnesia (1); angina (1); anxiety disorder (1); Aphasia (1); apraxia (1); atopic eczema (1); autoimmune disease (1); Charcot-Marie-Tooth disease (1); cognitive decline (1); cognitive disease (1); congenital diaphragmatic hernia (1); Cornelia de Lange syndrome (1); coronary heart disease (1).
A further 36 diseases each share a sentence with NRXN1 in 1 paper.